LEP (leptin)
Diseases named in the same sentence as LEP in open-access papers (continued):
Sharing a sentence is not in itself a finding about the gene and the disease.
breast tumor (continued). "Subgroup analysis of the multivariate associations of LEP, LEPR, ADIPOQ, ADIPOR1, and ADIPOR2 IHC expression with breast tumor clinicopathologic features among Black women yielded similar findings." (PMID 32046756, 2020). "Our bioinformatics results analyze publicly available genomic data to describe the expression of FGFR1 and leptin in breast tumors." (PMID 33019728, 2020). "It is also interesting to note that leptin, another well-known adipokine, promotes breast tumor growth through NLRP3 inflammasomes activation." (PMID 32155890, 2020). "The novelty of our findings disclose leptin/leptin receptor signaling as one of the main adipose-derived microenvironmental mediators that deeply affects breast tumor biology." (PMID 32727138, 2020). "Leptin and its receptor have been shown to be positively expressed in primary breast tumors and lymph node metastasis via IHC7." (PMID 30803210, 2019). "Further investigations showed that leptin, as a prominent adipokine, has an essential role in breast tumor prognosis, advanced stage, and metastasis." (PMID 29531546, 2017). "Inactivation of destruction complex allows accumulation and nuclear translocation of β-catenin, alteration of responsive gene expression and ultimately induces growth and metastatic progression of breast tumors in response to leptin treatment." (PMID 26036628, 2015). "Breast tumors treated with HNK also showed reduced expression of mesenchymal markers even in the presence of leptin treatment providing in vivo evidence." (PMID 26359358, 2015). "Leptin and adiponectin, which are both secreted by adipose tissue and often by breast tumors, act via a number of downstream signaling pathways involved in cell proliferation, apoptosis, cell-cycle regulation, angiogenesis, and cell survival." (PMID 22295251, 2012). "It remains to be evaluated if the frequent coexpression of leptin and ObR in breast tumors indeed reflects patient's adiposity." (PMID 18945363, 2008). "In particular, an elevated leptin level due to dysfunctional adipose tissue may induce activation of dormant breast tumor cells." (PMID 37571390, 2023). "This may indicate an important role for leptin in stimulating the growth and progression of primary breast tumour cells, especially in obese women." (PMID 36556428, 2022). "Interestingly, mice treated with tamoxifen and leptin exhibited higher tumor growth similar to leptin alone group showing that leptin exposure renders breast tumors unresponsive to tamoxifen." (PMID 34389732, 2021). "In addition, future studies are needed to further elucidate the mechanism by which lipid metabolic rewiring modulates breast tumor growth by leptin." (PMID 33226729, 2021). "Leptin has been shown to promote breast tumor growth via autophagy induction." (PMID 33226729, 2021). "Herein, we demonstrate a relationship between FGFR1, leptin, and LepR in human breast tumors." (PMID 33019728, 2020). "Leptin might further regulate stress response and metabolism that cisplatin-induced cytotoxicity in breast tumor cell MCF-7 decreased by leptin alone with SIRT1 upregulation." (PMID 29682217, 2018). "Grade of breast tumors is marginally significant with leptin immunostaining (P = 0.050)." (PMID 29121911, 2017). "In leptin-treated breast tumors, a cross-talk between leptin and MTA1/Wnt signaling was observed that may be important in EMT." (PMID 27999207, 2017). "Leptin signaling also induced breast tumor cell proliferation in both human and mouse cell lines." (PMID 27042159, 2016). "Our studies show that HNK treatment inhibits leptin-induced breast tumor progression in vivo." (PMID 26036628, 2015). "Although as indicated leptin and leptin receptor expression have been identified in human breast tumors, proteins associated with leptin signaling have not been characterized." (PMID 18162139, 2007).
breast tumor (continued). "High leptin levels have been also correlated with lower chemosensitivity, and a common nexus between leptin and several mechanisms that come usually activated in breast tumors—such as VEGF and other pro-angiogenic pathways or estrogen/progesteron receptor signaling—have also been identified." (PMID 35681689, 2022). "Therefore, a high FGFR1/leptin/FGFR1 breast tumor signature may be most detrimental when circulating levels of FGFs and leptin are elevated." (PMID 33019728, 2020). "Building on our prior research, here we examined the associations of body fatness measures with protein and gene expression of the adipokines, LEP and ADIPOQ, and the adipokine receptors, LEPR, ADIPOR1, and ADIPOR2 in breast tumor tissues." (PMID 35846306, 2022). "Our findings suggest that measures of body fatness are associated with the expression of adipokine receptors – primarily LEP and LEPR – in breast tumors." (PMID 35846306, 2022). "Next, we compared the relationship between leptin mRNA and FGFR1 mRNA among primary breast tumors divided into subgroups according to FGFR1 copy-number level per gene expression by the Genomic Identification of Significant Targets in Cancer (GISTIC)." (PMID 33019728, 2020). "In conclusion, we define a positive relationship between leptin, LepR and FGFR1 in primary human breast tumors and a positive relationship between LepR and FGFR1 in the tissue adjacent to tumors." (PMID 33019728, 2020). "Displaying noteworthy in vivo efficacy against oncogenic effects of leptin, HNK treatment reduced breast tumor growth in leptin + HNK treated experimental group." (PMID 26036628, 2015). "Together, these results demonstrate that HNK treatment results in effective suppression of leptin-induced breast tumor growth suggesting that HNK is a novel and effective leptin-antagonist." (PMID 26036628, 2015). "Overall, our findings demonstrate a novel SFK/ERK1/2-mediated pathway that links leptin signalling and expression of oncogenic enzyme SK1 in breast tumours and suggest the potential significance of this pathway in ER-negative breast cancer." (PMID 25482303, 2014). "In conclusion, our results suggest that breast tumor cells experience hypoxic conditions, as indicated by the expression of such markers as HIF-1α, Glut-1, leptin and ObR." (PMID 20569445, 2010). "Leptin-dependent activation of the HER2 receptor could be explained by the co-localisation of leptin and HER2 receptors in HER2+ cell lines and human breast tumours." (PMID 37173907, 2023). "Variation in LEPR IHC expression was observed by breast tumor clinicopathologic features, while the expression of LEP, ADIPOQ, ADIPOR1, and ADIPOR2 did not appear to vary by tumor clinicopathology." (PMID 32046756, 2020). "Interestingly, significantly higher leptin levels were observed in FGFR1 amplification, gain, and diploid ER- tumors compared with these copy number states in ER+ breast tumors (p < 0.05)." (PMID 33019728, 2020). "Moreover, adipocyte-derived leptin was approved to propel self-renewal of BC stem cells and chemoresistance via activating JAK/STAT3-regulated fatty acid β-oxidation (FAO) in mouse breast tumors in vivo." (PMID 32787888, 2020). "Herein, we found that, of all primary tumors in 29 different tissues, primary breast tumors demonstrated the most significant relationship between leptin mRNA and FGFR1 mRNA and had the highest levels of average leptin mRNA among other primary cancers of comparison." (PMID 33019728, 2020). "Leptin, an adipokine, can de-stable HIF-1α and stimulate hypoxia condition in breast tumors." (PMID 31398937, 2019). "Nutritional interventions or anti-leptin treatment may be considered as a potential preventative strategy and treatment for HER-2/neu overexpressing breast tumors, respectively." (PMID 24959279, 2014).
breast tumor (continued). "Leptin enriched in mammary adipocytes could downregulate CD8+ T cell effector functions through activating STAT3-FAO and inhibiting glycolysis, leading to inhibition of breast tumor development." (PMID 32787888, 2020). "Also, leptin overexpression was observed in 92% of breast tumors examined but in none of the cases of normal breast epithelium." (PMID 26359358, 2015). "However, while breast tumour cells proliferate after leptin stimulation, transgenic mice with no leptin or its receptor have been shown to be resistant to tumour formation." (PMID 24073332, 2013). "Glut-1 did not correlate with leptin or ObR in any studied group of breast tumors." (PMID 20569445, 2010). "In patients with non-luminal type breast tumors (HER2-positive and triple-negative), serum concentration of leptin is 55 pg/ml compared to 48 pg/ml in luminal type, statistically significant, p=0.0168." (PMID 35989732, 2022).
Autoimmunity (52 papers, 2009 to 2025). The occurrence of an immune reaction against the organism's own cells or tissues. "Aside from signaling energy balance, however, leptin has been implicated in inflammation and autoimmunity." (PMID 37628676, 2023). "Studies of leptin or leptin receptor deficient mouse models have revealed striking protection from autoimmune development in many models of induced autoimmunity." (PMID 36479348, 2022). "The lupus-inducing agent pristane was used to trigger autoimmunity in leptin-deficient (ob/ob) mice." (PMID 36479348, 2022). "Chronic leptin- and leptin-receptor deficiency is correlated with resistance to autoimmunity and high susceptibility to infection." (PMID 30795546, 2019). "Within the CNS, leptin signaling in macrophages is associated with a worse CNS autoimmunity course based on data in experimental autoimmune encephalomyelitis (EAE), namely through increased leptin expression by macrophages within the peripheral secondary lymphoid organs." (PMID 41516046, 2025). "As a result, a diet associated with increased levels of leptin could possibly influence the balance between T cells, promoting inflammation and inducing cell-mediated autoimmunity." (PMID 35334810, 2022). "Although little research has been done during pregnancy, it has been found that obese people tend to have higher serum leptin concentration, and many studies have indicated that high leptin levels may be associated with autoimmunity." (PMID 26273610, 2015). "Increased levels of leptin are associated with inflammation and autoimmunity." (PMID 23343052, 2013). "Aging is associated chronic inflammation and autoimmunity, and increased levels of leptin." (PMID 23343052, 2013). "In patients with generalized lipodystrophy, these potentially include the development of antibodies that neutralize endogenous leptin and/or metreleptin, lymphoma, hypoglycaemia, autoimmunity and hypersensitivity." (PMID 40616697, 2025). "Adipokines modulate the functions of immune cells and their cytokine repertoire in Pso; among these, leptin, resistin, and adiponectin are key regulators of immune dynamics in autoimmunity." (PMID 40893809, 2025). "In leptin resistance, peripheral proinflammatory signaling is maintained while central leptin signaling is restricted, thereby potentially promoting autoimmunity in MS and limiting neuroprotection in AD." (PMID 41516046, 2025). "Physiologically supportive of competent immunity, high leptin level in excessive or chronic states has the potential to destabilize antibody quality and promote autoimmunity." (PMID 41516046, 2025). "This heightened leptin level suggests altered autoimmunity shielding pregnant women from SARS-CoV-2." (PMID 39062978, 2024). "Increased leptin in humans has been suggested to be related with proinflammatory conditions and autoimmunity." (PMID 35334810, 2022). "Numerous studies have demonstrated that leptin enhances activation of both arms of the immune system, while its absence protects against development of autoimmunity." (PMID 36479348, 2022). "AlsoFurthermore, leptin inhibits the differentiation of Treg cells, which are a potent inhibitor of autoimmunity." (PMID 33673730, 2021). "Researches showed that Treg cells are affected by leptin and involved in the control of autoimmunity and thyroid cell apoptosis." (PMID 32256575, 2020). "Further, the same group has demonstrated a selective and cell intrinsic requirement for leptin during autoimmunity to upregulate glucose metabolism so that the effector functions of T cells are controlled." (PMID 31736971, 2019). "Our results indicate that leptin is required for human immune homeostasis and contributes to autoimmunity in a TNFα-dependent manner." (PMID 31822667, 2019). "For that reason, leptin has been identified as a key regulator of both protective immunity and autoimmunity in the context of nutritional disorders." (PMID 29868016, 2018).
Autoimmunity (continued). "In animal models with autoimmunity and infectious diseases, leptin regulates Th1/Th2/Treg balance to control the disease." (PMID 29868503, 2018). "In a spontaneous animal model of SLE, the administration of leptin promoted acceleration of the disease, whereas functionally reducing leptin protected animals from the development of autoimmunity." (PMID 30169503, 2018). "From clinical point of view, serum leptin levels have been evaluated in several autoimmune conditions." (PMID 24900992, 2014). "In contrast, leptin might also directly promote T-cell glycolytic metabolism to drive effector T-cells in a mouse model of autoimmunity, indicating a complicated function of leptin T cell biology." (PMID 37006245, 2023). "In addition, increased leptin, as a result of weight gain, can mediate autoimmunity by preferential up-regulation of autoreactive T cells and down-regulation of Treg cells, mediating a suppressive effect on the immune system." (PMID 33746952, 2021). "This suggests that leptin inhibition can reduce autoimmunity in SLE patients." (PMID 33673730, 2021). "In experimental studies, it has been suggested that high levels of adipocytokines such as leptin could be related to the development of autoimmunity in obese SLE-prone mice." (PMID 31698711, 2019). "Our results now indicate that, in the setting of a pre-existing inflammatory condition, leptin therapy fuels inflammation and increases disease activity in autoimmunity via the induction of TNFα-producing cells and by metabolically priming immune cells towards a pro-inflammatory phenotype." (PMID 31822667, 2019). "Moreover, leptin modulates the activity of Treg cells, which are potent inhibitors of autoimmunity, thus having a potential implication in RA pathophysiology." (PMID 29910742, 2018). "Considering the regulatory effects of leptin on Th17 and Treg populations, revoking leptin signaling might be a potential therapeutic approach for inflammation and autoimmunity." (PMID 29910742, 2018). "This implies that leptin, which plays an important role in food consumption, may also play a role in immune suppression and autoimmunity." (PMID 27401171, 2016). "Leptin, an adipocyte-derived hormone, plays a role in immune responses and promotes autoimmunity." (PMID 24900992, 2014). "CD5+ B cells are reported to produce IL-10 with immunoregulatory property, which may explain a role of leptin in autoimmunity." (PMID 23343052, 2013). "Although leptin resistance presented early in BWF1 mice can slow-down the progression of autoimmunity, our results suggest that sustained insulin stimulation of organs, such as liver and probably kidneys, facilitates the over-expression and activity of mTOR and the development of SLE." (PMID 23226562, 2012). "One such example is the apparent role played by leptin in the development of autoimmunity." (PMID 19888448, 2009). "Interestingly, Treg cells could be influenced by leptin, and leptin could downregulate the proliferation of a Treg subpopulation involved in the control of autoimmunity and thyroid cell apoptosis." (PMID 33381173, 2020). "Concentration-dependent effects of estrogen on the immune system; the role of progesterone, androgens, leptin, oxytocin, and prolactin; and the interplay between Th1 and Th2 immune responses together maintain a delicate balance between host defense, immunological tolerance and autoimmunity." (PMID 31110493, 2019). "Therefore, the strategic usage of Tregs with the manipulation of leptin signaling may provide a new opportunity to control infectious and autoimmunity disorders." (PMID 29868503, 2018). "Leptin, an adipokine that is increased in obese persons, has been shown to accelerate immune-modulated destruction of beta cells in mice, and obese individuals have lower concentrations of the adipokine adiponectin that was shown to protect beta cells from apoptosis and autoimmunity in animals." (PMID 28763444, 2017).
Autoimmunity (continued). "In addition leptin is implicated in the susceptibility to autoimmune and infectious diseases, given the association of increased leptin levels with chronic inflammation, autoimmune conditions and increased frequency of infections and given the inhibition of autoimmunity by decreased leptin levels." (PMID 24084730, 2013). "Hence, leptin could represent the “missing link” between autoimmunity and nutritional status." (PMID 24106499, 2013). "Leptin levels are elevated in both MS patients and in EAE models, where higher concentrations correlate with relapse rates, disability progression, and EDSS scores, suggesting a potential role in driving autoimmunity." (PMID 41516046, 2025). "Growth factors acting on nutrition—leptin, insulin and insulin-like growth factor 1 (IGF-1) activate mTOR signaling in immune cells, and thus regulate immunometabolism, and when impaired contribute to inflammation and autoimmunity." (PMID 39599673, 2024). "Indeed, there are numerous theoretical premises that high plasma leptin, a hormone produced mainly in white adipose tissue, by activating effector T lymphocytes and inhibiting regulatory T lymphocytes, may favor the occurrence of autoimmunity in obese patients." (PMID 37512046, 2023). "It is possible that leptin, CRP, or IL-6 levels may be confounded by ethnic differences in inflammatory or autoimmune conditions; however, this is unlikely given that the women in this study were apparently healthy and relatively young." (PMID 21331287, 2011). "In the context of autoimmunity, it is likely not physiological leptin levels, which may even be beneficial in conditions such as AD, but rather persistently elevated leptin levels that may confer risk." (PMID 41516046, 2025). "Finally, there is a strong suggestion that leptin could also act as a negative signal and unfavorable regulator for the proliferation of Treg cells which normally suppress autoimmunity." (PMID 33381173, 2020).